SLC6A16 (solute carrier family 6 member 16)
Synonyms: NTT5; NT5
Tractability: Small molecule: it belongs to a druggable protein family. Antibody: UniProt predicts a signal peptide or a membrane-spanning region; its Gene Ontology location is reachable by antibodies, with medium confidence.
Gene: Protein-coding gene on chromosome 19 (49,289,638 to 49,325,215, reverse strand). Ensembl gene ENSG00000063127.
Subcellular location: Membrane
Subcellular location (Human Protein Atlas): Golgi apparatus
Gene Ontology:
Molecular function: neurotransmitter transmembrane transporter activity; transmembrane transporter activity
Biological process: amino acid transport; neurotransmitter transport; sodium ion transmembrane transport
Cellular component: plasma membrane; membrane
Genetic constraint (gnomAD): Loss-of-function variants: 54 observed, 72.21 expected, observed/expected ratio (o/e) 0.75, 90% interval 0.6 to 0.94. The upper end of that interval is the gene's LOEUF score, 0.94, which puts it in group 3 of 6, group 1 being the genes least tolerant of losing a copy. Missense variants: 816 observed, 963.47 expected, observed/expected ratio (o/e) 0.85, 90% interval 0.8 to 0.9. Synonymous variants: 330 observed, 366.86 expected, observed/expected ratio (o/e) 0.9, 90% interval 0.82 to 0.99.
Homologues: Orthologues: chimpanzee SLC6A16 (99% identical), macaque SLC6A16 (90% identical), dog SLC6A16 (62% identical), mouse Slc6a16 (46% identical), rat Slc6a16 (46% identical). Paralogues in human: SLC6A17 (32% identical), SLC6A15 (31% identical), SLC6A19 (28% identical), SLC6A18 (26% identical), SLC6A20 (26% identical), SLC6A2 (23% identical), SLC6A13 (23% identical), SLC6A6 (23% identical), SLC6A14 (22% identical), SLC6A5 (22% identical), SLC6A7 (22% identical), SLC6A3 (22% identical), and 6 more.